PTGS2 (prostaglandin-endoperoxide synthase 2)
Diseases named in the same sentence as PTGS2 in open-access papers (continued):
Sharing a sentence is not in itself a finding about the gene and the disease.
prostate carcinoma (41 papers, 1997 to 2025). A carcinoma that arises from epithelial cells of the prostate gland. "While those with the PTGS2 765 G/G variant (lower inflammatory activity) exhibited a decreased risk of advanced prostate cancer with higher dark fish (higher in n-3 LC-PUFA) consumption." (PMID 32498320, 2020). "The authors hypothesize that the C allele may be responsible for increased PTGS2 activity (hence greater inflammation) and that interactions with heterocyclic amines may have further increased inflammatory pathways and prostate cancer risk." (PMID 32498320, 2020). "This study investigated the potential association between the single nucleotide polymorphism (SNP) -842A>G (rs10306114) of the PTGS1 gene and SNP-765G>C (rs20417) of the PTGS2 gene with prostate cancer (PCa) and benign prostate hyperplasia (BPH)." (PMID 40184332, 2025). "Specifically, GEPIA showed PTGS2 downregulation in bladder, breast, colon, lung, and prostate cancers and upregulation in oesophageal carcinoma, stomach adenocarcinoma, and head and neck squamous cell carcinoma." (PMID 40444088, 2025). "More recently, an assay that evaluates the methylation of GSTP1, SFRP2, IGFBP3, IGFBP7, APC and PTGS2 genes to specifically identify individuals with a severe probability of developing prostate cancer has been proposed." (PMID 37511475, 2023). "DU-145 prostate cancer cells respond to TNF-α treatment with an increased expression of PTGS2, of COX-2 and of PGE2 production and this is accompanied by a decreased expression of NAPEPLD without change in NAAA or FAAH expression, thereby producing an imbalance in PTGS2/NAPEPLD." (PMID 33172176, 2020). "Immunohistochemical information from the HPA database showed that higher staining of GSTM4, PLP1, and PTGS2 was found in normal prostate tissue, while higher staining of SLC27A2, SLC45A3, APOE, and ABCC4 was observed in prostate cancer tissue." (PMID 40861808, 2025). "On the contrary, PTGS2, CLDN1, and RPPH1 are negatively correlated with the prognosis of prostate cancer." (PMID 35813821, 2022). "Another aspect of FAN analysis relevant to its utility and implications for the role resveratrol plays in prostate cancer relates to the three primary targets of resveratrol: CSNK2A1, NQO2 and PTGS2." (PMID 27232943, 2016). "We also found >2 fold signal in genes previously identified as methylated in prostate cancer such as CDKN2A (average of 15.8 fold enrichment), RUNX3 (2.8 fold), and PTGS2 (2.9 fold)." (PMID 19283074, 2009). "Multiple follow-up studies revealed that PTGS2 (COX-2) levels are elevated in other premalignant and malignant solid tumors, including stomach, esophagus, liver, pancreas, head and neck, lung, breast, and prostate cancer." (PMID 24213116, 2011). "In addition, PTGS2 inhibitors, a key enzyme in prostaglandin biosynthesis, resulted in decreased recurrence and mortality in patients with breast (NCT00525096, NCT02429427) and prostate cancer (NCT00316927)." (PMID 37888486, 2023).
glioma (39 papers, 2015 to 2025). A benign or malignant brain and spinal cord tumor that arises from glial cells (astrocytes, oligodendrocytes, ependymal cells). "For example, PTGS2, an enzyme involved in prostaglandin synthesis, has been implicated in radiation resistance in human glioma." (PMID 39794971, 2024). "The results showed that the PTGS2 gene polymorphism might be linked to the susceptibility of glioma in the Chinese population." (PMID 35154340, 2021). "Overexpression of systemic immunosuppressive soluble factors by glioma cells, such as PTGS2 (rate-limiting step catalyzed by COX-2), TGFB1, IDO1, and IL-10, were also investigated at the transcriptional level." (PMID 37322408, 2023). "The mRNA expression of PTGS1 (COX1) and PTGS2 (COX2) is presented for differing grades of glioma using the Gliovis data portal for visualization and analysis of brain tumor expression datasets to analyze data from the TCGA and the CCGA." (PMID 33919029, 2021). "The author selected 199 adult glioma patients confirmed by histology and 199 cancer-free controls as the objects of this study and analyzed the distribution of PTGS2 genotypes and haplotypes." (PMID 35154340, 2021). "Many aggressive aspects of GBM such as cell proliferation and poor prognosis are highly correlated with the expression of PTGS2 and it is overexpressed in radiation resistance glioma." (PMID 33803224, 2021). "Here, we sought to investigate PTGS2 upregulation to explore the ability of NF‐κB signaling on the regulation of glioma cell activities." (PMID 30740906, 2019). "PTGS2/NF‐κB signaling pathway was involved in radio‐tolerance of glioma cells, which provided a new insight into glioma therapy." (PMID 30740906, 2019). "We focused on the effects of PTGS2/NF‐κB signaling pathway on the radiation resistance of glioma in the study." (PMID 30740906, 2019). "In this research, we discovered that the expression of the PTGS2 was upregulated in radiation‐resistant glioma cells." (PMID 30740906, 2019). "Namely, Ptgs2 inhibits apoptosis in glioma xenografts, while Fap over-expression increases astrocytoma resistance to FAS-mediated apoptosis." (PMID 26517510, 2015). "PTGS2 is another hub gene which was enhanced in radiation resistant glioma cells." (PMID 33803224, 2021). "We hypothesized that NF‐κB signaling pathway could influence radiotherapy tolerance of glioma cells through regulating PTGS2, which may imply potential therapeutic approaches for the treatment of glioma." (PMID 30740906, 2019). "We hypothesized that PTGS2 was involved in the radioresistance of glioma, and subsequent experiments were carried out." (PMID 30740906, 2019). "In conclusion, PTGS2 might be involved in the radioresistance of gliomas." (PMID 30740906, 2019). "The effect of PTGS2 in other glioma cell lines and animal models could be further explored." (PMID 30740906, 2019). "Two complexes, the ESR2-isoflavanone complex and the PTGS2-1,7-Dihydroxy-3,9-dimethoxy pterocarpene complex, had the lowest binding affinities (−9.6 kcal/mol), suggesting that they could be the main active ingredients and targets of Astragalus membranaceus in the treatment of glioma." (PMID 38003496, 2023). "The STRING analysis results showed that PTGS2 was involved in a plenty of PPI networks, suggesting its potential involvement in the radioresistance of glioma." (PMID 30740906, 2019). "Further analysis using STRING identified four main gene networks (IL-6, BCL2, PTGS2 and CXCR4) that were downregulated in glioma cells silenced for RTVP-1." (PMID 26267319, 2015). "The author showed that five genes (SOD1, CAT, GSTP1, PTGS2, TNF), two miRNAs (hsa-miR-26b-5p and hsa-miR-143-3p), and transcription factors (DR1 and HNF4) are possible key components related to combined heavy metals and glioma development." (PMID 37895109, 2023).
Alzheimer disease (36 papers, 2005 to 2025). A progressive, neurodegenerative disease characterized by loss of function and death of nerve cells in several areas of the brain leading to loss of cognitive function such as memory and language. "Animal experiments have shown that the upregulation of PTGS2-induced inflammation can promote the progression of Alzheimer’s disease, and inhibiting the upregulation of PTGS2 can improve postoperative cognition." (PMID 39903567, 2025). "The expression of PTGS1 and PTGS2 changes throughout the progression of Alzheimer’s disease pathology and is believed to contribute to the neuroinflammatory aspect of the disease." (PMID 38977662, 2024). "In Alzheimer’s disease, lncMALAT1 negatively regulates the expression of Mir-125b-mediated PTGS2, while miR-103 promotes nerve recovery and growth by targeting PTGS2." (PMID 38671843, 2024). "Circ_0000950 accelerated neuron apoptosis, inhibited the outgrowth of neurite and enhanced the levels of inflammation-related cytokines via miR-103/PTGS2 axis in Alzheimer’s disease." (PMID 33393621, 2021). "It was also found that miR-103 promotes neurite outgrowth and reduces cell apoptosis by targeting prostaglandin-endoperoxide synthase 2 (PTGS2) in cellular models of Alzheimer’s disease." (PMID 30423818, 2018). "This cell-based litmus gene assay identified six genes (CCL20, CEMIP, IL1B, IL8, PRG2, PTGS2) as potential biomarkers of plasma quality control and the SPC25 gene as a diagnostic biomarker of Alzheimer’s disease (AD)." (PMID 29203810, 2017). "Ptgs2 has been reported to be a vital biomarker of neuroinflammation in Alzheimer's disease." (PMID 33628784, 2021). "Genes whose mRNA levels decline with age have significantly greater promoter DNA damage, so some mechanism may prevent normal downregulation of PLA2G4A and PTGS2 in Alzheimer's disease." (PMID 24963629, 2014). "FOXQ1 also reportedly binds directly to inhibit prostaglandin-endoperoxide synthase 2 (PTGS2), and cyclin-dependent kinase 5 (CDK5) to promote apoptosis and inflammation while inhibiting neurite outgrowth in Alzheimer Disease." (PMID 41347087, 2025). "Diving deeper into to the evidence chains, Sulindac, an inhibitor of PTGS1 and PTGS2, has been predicted as a potential therapy for FXS by linking these two proteins to their involvement in Alzheimer’s disease and amyloid precursor protein (APP) processing." (PMID 38977662, 2024). "The Alzheimer disease pathway is the second-ranked signaling pathway, and 5 key targets, CASP9, APP, NOS2, NOS1 and PTGS2, are enriched in this pathway." (PMID 37904435, 2023). "CASP9 and PTGS2 in neurodegeneration_multiple diseases, NOS1, NOS2 in Alzheimer disease pathway were identified as core targets." (PMID 37904435, 2023). "mRNA and protein levels of cPLA2 IVA (PLA2G4A), sPLA2 IIA (PLA2G2A), COX-1 and -2 (PTGS1, PTGS2), mPGES1 (PTGES1), and LOX-12 and -15 (ALOX12B, ALOX15B), are increased in Alzheimer's disease in the frontal cortex, hippocampus, and cerebellum." (PMID 24963629, 2014). "Healthy brain aging does not show upregulation of PLA2G4 or PTGS2 expression, which was found in Alzheimer's disease." (PMID 24963629, 2014).
depression (36 papers, 2013 to 2026). "There is a close association between PTGS2 and depression, involving multiple aspects, including neuroinflammation, neurotransmitter metabolism, neuroplasticity, and hypothalamic–pituitary–adrenal (HPA) axis function." (PMID 40491976, 2025). "IL-17 A-induced inflammatory mediators, including IL-6, IL-1β, Ptgs2, Csf2, and Cxcl1, can cause myocardial inflammation and depression [,14], and have been associated with endotoxin-induced cardiac dysfunction and shock [14,]." (PMID 41311862, 2025). "Of note, the average hub gene inference scores are higher in depression compared to vitamin D deficiency, with the maximum for PTGS2." (PMID 38256187, 2024). "This study also examined PTGS2, which is strongly associated with inflammatory processes in the course of depression." (PMID 36012250, 2022). "Among these core targets, SIRT1, HIF1A, ESR1, VEGFA, HSP90AA1 and PTGS2 are well documented to be associated with depression." (PMID 36496991, 2022). "In reference to effect of combined genotypes, it was found that G/G-T/T genotypes of g.70677994G>A (rs2166975)—TGFA and g.186640617C>T (rs4648308)—PTGS2 was associated with decreased risk of depression occurrence, while A/G-C/T genotypes increased this risk." (PMID 32140313, 2020). "Furthermore, in a model depression in adult rats caused by neonatal treatment with the antidepressant drug clomipramine, PTGS2 mRNA expression was increased in the hippocampus." (PMID 33946816, 2021). "Another gene believed to be associated with mechanisms of depression is PTGS2." (PMID 33946816, 2021). "Furthermore, in male population allele G and G/G homozygote of the g.186643058A>G (rs5275) of PTGS2 decreased risk of depression while, allele A and A/A homozygote of the same polymorphism was associated with increased risk of the occurrence of the disease." (PMID 32140313, 2020). "Increased enzyme activity of PTGS1 and PTGS2 has been implicated as another mechanism in depression, and herb drugs reducing arachidonic acid levels through inhibiting PTGS1/2 could be used to treat depression in the chronic unpredictable mild stress rat model." (PMID 34829725, 2021). "Future research should prioritise evaluating these inhibitors in preclinical models of depression, examining their effects on ferroptosis markers (e.g., GPX4, PTGS2, lipid ROS), synaptic integrity, and depression‐related behaviours." (PMID 41311024, 2025). "In summary, our study demonstrated that cAMP/PKA/CREB/PTGS2 is one of the potential signaling pathways for depression treatment." (PMID 40491976, 2025). "The regulatory effect of AE on the cAMP/PKA/CREB/PTGS2 signaling pathway suggested its ability to address multiple aspects of depression." (PMID 40491976, 2025). "Our CytoHubba analysis identified six hub genes (PECAM1, TLR2, PTGS2, LRRK2, HCK, and IL18), all significantly upregulated in both depression and hypovitaminosis D, with PTGS2 having the highest inference score and reference count." (PMID 38256187, 2024). "Elevated levels of PTGS2 and proinflammatory prostaglandins have been observed in individuals with depression." (PMID 38567354, 2024). "PTGS2, known for encoding Cyclooxygenase-2 (COX-2), has a significant role in inflammatory responses and is linked to conditions like depressive disorder, esophageal neoplasms, cerebrovascular accidents, and coronary artery disease." (PMID 39337647, 2024). "The imbalance in PTGS2-BDNF signaling pathway has been suggested to be one of the pathogenetic mechanisms of depression." (PMID 35911513, 2022). "The six predominant targets (TNFα, ESR1, TLR4, PTGS2, MMP9 and NOS3) have been well documented to associate with depression." (PMID 35626632, 2022). "PTGS2 and its downstream product PGs play important roles in triggering an inflammatory cascade in depression." (PMID 33946816, 2021).
depression (continued). "Nevertheless, our findings confirm at least a partial association between TGFA, TGFB, PTGS2, IRF1 and IKBKB genes and depression, and hence it is highly likely that inflammation plays a role in psychiatric disorders." (PMID 33946816, 2021). "Summarizing, our results confirm at least a partial association between TGFA, TGFB, IRF1, PTGS2 and IKBKB and depressive disorders." (PMID 33946816, 2021). "The upregulation of the PTGS2 gene observed in the course of depression, together with the effectiveness of its inhibitors in therapy, confirm that PTGS2 plays a role in developing depressive disorders." (PMID 33946816, 2021). "Distribution of genotypes and alleles of rs2070729 (IRF1), rs5275 (PTGS2), rs4648308 (PTGS2), rs2166975 (TGFA), rs5029748 (IKBKB) and the risk of depression occurrence in male and female population." (PMID 32140313, 2020). "Distribution of genotypes and alleles of rs1800469 (TGFB1), rs2070729 (IRF1), rs5275 (PTGS2), rs4648308 (PTGS2), rs2166975 (TGFA), rs5029748 (IKBKB) and the risk of depression occurrence." (PMID 32140313, 2020). "The trend of increasing risk of depression prevalence is also present in the case of linked genotypes of rs5029748—IKBKB and rs4648308—PTGS2." (PMID 32140313, 2020). "Gene-gene interactions of rs1800469 (TGFB1), rs2070729 (IRF1), rs5275 (PTGS2), rs4648308 (PTGS2), rs2166975 (TGFA), rs5029748 (IKBKB) and the risk of depression occurrence." (PMID 32140313, 2020). "This increase in PTGS2 levels underscores its potential role in the pathophysiology of depression." (PMID 40491976, 2025). "Interestingly, compared to the control cells, the level of PTGS2 was elevated in the CORT‐induced depression cell model." (PMID 40491976, 2025). "The findings indicate that the cAMP/PKA/CREB/PTGS2 signaling pathway plays a crucial role in the antidepressant effects of AE, paving the way for its potential clinical application as a novel treatment for depression." (PMID 40491976, 2025). "Furthermore, with the gradual discovery of the link between depression and inflammation, the PTGS2 inhibitors have been demonstrated to facilitate the therapeutic effects of antidepressants." (PMID 36440424, 2022). "Concluding, our results indicate that TGFA, TGFB, PTGS2, IRF1 and IKBKB could be associated with depression and its treatment." (PMID 36012250, 2022). "Importantly, research on an animal model of depression confirmed that PTGS2 levels are significantly elevated in various brain regions." (PMID 33946816, 2021). "In this research, we genotyped six polymorphic variants of TGFA, TGFB1, IRF1 and PTGS2 genes; and to our knowledge, none of this SNPs have been studied in the context of severity and treatment response in depression before." (PMID 32140313, 2020). "Additionally, in animal model of depression increased expression of PTGS2 was observed in brain regions." (PMID 32140313, 2020). "Moreover, TGFB is known to play a neuroprotective role, especially in neurodegenerative disorders as well as stimulate prostaglandin-endoperoxide synthase 2 (PTGS2; cyclooxygenase-2—COX-2) encoded by the PTGS2 gene, which is associated with depression etiology and progression." (PMID 36012250, 2022). "Our miRNA-TFs-hub genes network advances several novel molecular targets like PTGS2, LRRK2, miR-146a-5p, and miR-181c-5p, which might contribute to the development of novel diagnostic, monitoring, and therapeutic strategies in (hypovitaminosis D-related) depression." (PMID 38256187, 2024). "This study predicted that linalool, p-cymene, α-terpinene, terpinen-4-ol, and α-terpineol primarily contribute to CBEO’s anti-depressant effect, mainly via interactions with OPRM1, PTGS2, ESR1, SLC6A4, DRD2, and NR3C1, the six depression-related targets." (PMID 38567354, 2024).
depression (continued). "In this study, after conducting network-feature topology analysis on the PR candidate compounds–depression targets network, it was found that COX2 and PTGS2 have the same degree value, which is the largest value among the targets." (PMID 38674858, 2024). "This study focuses on the contribution of genes such as IRF1, PTGS2, IKBKB, TGFA and TGFB in the molecular basis of depression as well as the impact of chronic agomelatine administration." (PMID 36012250, 2022). "Thus, our study suggested that alongside the improvement of cognitive functions and depression‐like behaviors, AE treatment showed a regulatory effect on the cAMP/PKA/CREB/PTGS2 signaling pathway in CUMS mice." (PMID 40491976, 2025). "Our key findings reveal that TGFA, TGFB, PTGS2, IRF1 and IKBKB could be responsible for immune system activation in depression." (PMID 36012250, 2022).